VHL (von Hippel-Lindau tumor suppressor)
Diseases named in the same sentence as VHL in open-access papers (continued):
Sharing a sentence is not in itself a finding about the gene and the disease.
hemangioblastoma (continued). "Second, we observed that hemangioblastomas share similar histomorphological features with the hemangioblast, such as blood island formation and extramedullary hematopoiesis (with VHL-deficient daughter cells)." (PMID 37174017, 2023). "Craniospinal hemangioblastoma occurs in over 80% of patients with VHL-associated hemangioblastoma, and multiple lesions occur in over 90% of patients." (PMID 36760665, 2022). "The first is the case of a 31-year-old female with a confirmed pathogenic germline variant in the VHL gene, with multiple intracranial lesions and a cervical spinal cord lesion all compatible with hemangioblastoma." (PMID 35819008, 2022). "The first case is a 31-year-old female with confirmed pathogenic germline VHL mutation who presented with multiple hemangioblastomas." (PMID 35819008, 2022). "Deletion of VHL alleles and certain type 2B VHL missense mutations resulted in an increased risk for hemangioblastoma and RCC formation." (PMID 35205407, 2022). "VHL-associated hemangioblastomas tend to appear at a younger age than sporadic forms (30–40 years vs. 50–70 years), but both are primarily seen in adults." (PMID 35199211, 2022). "The purpose of this study was to explore the genotype-phenotype, clinical features, treatment and follow-up of VHL-associated hemangioblastomas in pediatric patients." (PMID 34109129, 2021). "One patient from this group (F14) without either TRAF7, KLF4, or AKT1 mutations harbored a germline VHL mutation with VHL copy number loss in the tumor, and developed posterior fossa chordoid meningioma followed by hemangioblastoma 12 years later." (PMID 31963394, 2020). "Both sporadic and VHL-associated hemangioblastomas are extremely rare in childhood (incidence < 1 per 1,000,000)." (PMID 32507909, 2020). "Molecular genetic investigation of 31 patients with hemangioblastomas revealed 29 patients (94%) with VHL germline mutation." (PMID 30214643, 2018). "These neoplastic cells can also be differentiated into multiple hematopoietic cell lineages, suggesting that VHL-associated hemangioblastomas are derived from mesoderm-derived, embryonically arrested hemangioblasts." (PMID 30234140, 2018). "Many surgeons find exception with one autosomal dominant familial cancer syndrome, VHL, which has been associated with nearly 30% of all hemangioblastomas and accounts for a more rapidly progressive tumor." (PMID 30345209, 2018). "A 64-year-old female with a germline VHL missense mutation (R167W), a known large suprasellar hemangioblastoma, and history of right eye enucleation presented with worsening vision of her remaining left eye." (PMID 28094316, 2017). "Causative mutations deactivate VHL which is a tumor suppressor gene, this leads to the development of hemangioblastoma in a number of CNS tissues." (PMID 29479522, 2017). "The characteristic vascularized appearance of hemangioblastomas in VHL-disease patients is thought to be caused by the VHL-mutation leading to defective or absent VHL protein (pVHL)." (PMID 26920352, 2016). "Our data show that in all VHL-related and in the majority of sporadic hemangioblastomas a mutation, LOH or hypermethylation of the VHL was present." (PMID 26920352, 2016). "The finding that CXCR4 expression was higher in sporadic hemangioblastomas is striking as in VHL-disease a germline mutation in VHL leads to a defect VHL protein which results in enhanced transcription of CXCR4, its ligand CXCL12 as well as VEGFA." (PMID 26920352, 2016). "For most VHL disease related hemangioblastomas, the inactivation or loss of both alleles of the VHL gene is required." (PMID 26768750, 2016). "In order to verify the contribution of somatic VHL mutations and hypermethylation of hemangioblastomas we analyzed VHL mutations and promoter methylation in the tumor tissue." (PMID 26920352, 2016). "This is the first study in which expression of CXCR4, CXCL12, and VEGFA is compared in both sporadic and VHL associated hemangioblastoma patients." (PMID 26920352, 2016).
hemangioblastoma (continued). "Previous studies reported inactivation of both alleles of VHL in 62 of VHL-disease related hemangioblastoma." (PMID 26920352, 2016). "Currently, vorinostat, an HDACi, is undergoing Phase I trials for VHL patients with hemangioblastomas and missense mutations, trial #NCT02108002." (PMID 27446927, 2016). "VHL hemangioblastomas are most commonly caused by germline exon deletions or truncating mutations of the Von Hippel-Lindau (VHL) tumor-suppressor gene." (PMID 26768750, 2016). "In 76.9 % of cases (10 out of 13) of VHL-related hemangioblastomas only the germline mutation was found, in 15.4 % (2 out of 13) two mutations were present (second hit) and in one case 3 mutations were found." (PMID 26920352, 2016). "The validation cohort consisted of 22 sporadic hemangioblastomas, for which the exons of 560 genes (including VHL and ARID1B) and 39 translocations previously implicated in cancer were sequenced at an average depth of 182x." (PMID 25589003, 2014). "One study identified concurrent somatic mutation and LOH of VHL in only 1 of 13 sporadic hemangioblastomas and another study identified missense mutations with deletion of VHL by comparative genomic hybridization in only 2 of 16 sporadic hemangioblastomas." (PMID 25589003, 2014). "Prior studies have reported the presence of mutations in VHL in 10 to 44% of sporadic hemangioblastoma." (PMID 25589003, 2014). "Together, these alterations account for biallelic inactivation of VHL in 47% and an inactivating alteration in at least one allele in 78% of sporadic hemangioblastomas." (PMID 25589003, 2014). "Inactivation of the VHL gene in affected VHL family members is responsible for their genetic susceptibility to hemangioblastoma." (PMID 28326249, 2014). "We considered two possibilities for this difference between the reported frequency of mutations in VHL between familial and sporadic hemangioblastomas." (PMID 25589003, 2014). "In the case series of VHL-associated hemangioblastomas, LC rates were 83–97%, 83% and 61% at 2, 5 and 10 years, respectively." (PMID 24554558, 2014). "Although the pathogenesis is incompletely understood, hemangioblastoma is generally believed to be a benign neoplasm originating in the CNS and associated with either germ-line or somatic mutations of the VHL gene on 3p25-26." (PMID 25574414, 2014). "Furthermore, VHL-associated hemangioblastomas typically exhibit earlier disease onset, and patients are generally younger at the time of treatment." (PMID 40091097, 2025). "On the other hand, this study offers preclinical evidence supporting acriflavine’s therapeutic potential for VHL-associated hemangioblastomas, based on patient-derived cell cultures, which are better at preserving original tumor characteristics than established cell lines." (PMID 40427061, 2025). "The involvement of both HIF-1α and HIF-2α in tumor growth and vascularization may explain why selective HIF-2α inhibitors like Belzutifan show limited efficacy in VHL-deficient hemangioblastomas." (PMID 40427061, 2025). "Our results therefore suggest that dual inhibition of HIF-1 and HIF-2 could represent a promising therapeutic approach for VHL-associated hemangioblastomas." (PMID 40427061, 2025). "Von Hippel-Lindau (VHL) disease is a hereditary condition caused by mutations in the VHL gene that lead to the development of vascular tumors such as clear cell renal cell carcinoma (ccRCC), central nervous system (CNS)-hemangioblastoma, and pancreatic neuroendocrine tumors (panNET)." (PMID 41024941, 2025). "The anesthetic management of parturients with VHL is challenging for clinicians, whether general or neuraxial anesthesia is used, as they face the risk of hemangioblastoma rupture." (PMID 41409938, 2025).
hemangioblastoma (continued). "Children of patients affected by VHL should be genetically tested at an early age as patients with truncating variant are associated with a nearly four times higher risk of hemangioblastoma development and threefold increased risk for surgical intervention compared to patients with missense variant." (PMID 38647646, 2024). "In addition to germline mutations in patients with VHL disease, somatic mutations of the VHL gene are also frequently found in sporadic hemangioblastomas." (PMID 38610939, 2024). "Similarly, VHL, which is mutated in pituitary stalk hemangioblastoma of VHL patients, decreases GLI1-mediated promoter transactivation and thus inhibits expression of HH signaling target genes." (PMID 37476499, 2023). "In addition, pituitary stalk hemangioblastomas can harbor VHL (Von Hippel-Lindau tumor suppressor) mutations." (PMID 37476499, 2023). "Based on these three observations, we have hypothesized that VHL-associated hemangioblastomas originate from developmentally arrested embryonic hemangioblasts containing a neoplastic potential and the protracted capacity to differentiate." (PMID 37174017, 2023). "Due to these common features, it is of major interest to investigate whether VHL-associated tumors other than hemangioblastoma also share these pathways and molecular features." (PMID 37174017, 2023). "Additionally, they showed that a small subset of VHL-deficient microscopic lesions extends beyond the nerve root to form early hemangioblastoma." (PMID 36556926, 2022). "Somatic VHL mutations have also been described in sporadic hemangioblastomas and paragangliomas." (PMID 36106637, 2022). "This is the first report of a pathogenic variant at intron 2 in VHL-associated hemangioblastomas." (PMID 33004005, 2020). "Therefore, to elucidate the mechanism involved in the loss of SDHB immunoexpression in hemangioblastoma, further comprehensive molecular genetic analyses of SDHx mutations, including promoter methylation and/or VHL testing, should be performed." (PMID 30971719, 2019). "In addition, three case series generated contradicting findings regarding the influence of pregnancy on growth of CNS hemangioblastomas in VHL mutation carriers." (PMID 31087189, 2019). "When mutations, deletions or LOH events involving the VHL locus are taken together, the discovery cohort of sporadic hemangioblastomas demonstrate biallelic inactivation of VHL in 6 of 10 cases and inactivation of at least a single allele of VHL in 8 of 10 cases." (PMID 25589003, 2014). "VHL mutations have been previously detected in sporadic hemangioblastomas." (PMID 25589003, 2014). "VHL gene mutations are also common in sporadic hemangioblastomas." (PMID 28326249, 2014). "Patients diagnosed with hemangioblastoma should be tested for VHL gene mutations." (PMID 23781388, 2013). "Analogous to our hypothesis, VHL-associated hemangioblastomas have been demonstrated to derive from embryologic multipotent cells." (PMID 19340311, 2009). "Approximately 25% of hemangioblastomas are associated with VHL." (PMID 20181189, 2009). "Hence, together these results suggest that dual inhibition of HIF-1α and HIF-2α could be a promising non-invasive strategy for the treatment of VHL-associated hemangioblastomas or as a complementary therapy to surgery." (PMID 40427061, 2025). "However, the study did not stratify cases by VHL status, and thus no conclusions could be drawn regarding the distribution of subtypes between VHL-associated and sporadic hemangioblastomas." (PMID 41382243, 2025). "The study revealed dilated vasculature in the brainstems of all the mice showing RHs, while no specific lesions were found in the kidney or pancreas, suggesting that embryonically derived hemangioblasts may be the common origin of both VHL-associated retinal and CNS hemangioblastomas." (PMID 39336783, 2024).
hemangioblastoma (continued). "Furthermore, our study reveals a strong association between hemangioblastoma in the CNS and the retina in patients with VHL-associated RH, implying that RH could potentially serve as an early indicator of CNS hemangioblastoma." (PMID 39336783, 2024). "Consequently, the onset of the disease is sped up to 11 years old and, along the following 12 years, he underwent 5 surgeries (10 hemangioblastomas), while his VHL mutation-bearing relatives (father and sister) had a much later onset and underwent 4 and 1 surgeries, respectively, in their life." (PMID 37843608, 2023). "Indeed, the more progressive epithelioid hemangioblastomas feature VHL-deficient vascular structures and extramedullary haematopoiesis, which may also explain tumor diversity in VHL disease." (PMID 37174017, 2023). "Central nervous system (CNS) hemangioblastomas are the most frequent cause of mortality in patients with Von Hippel–Lindau (VHL) disease, an autosomal dominant genetic disease resulting from germline mutations in the VHL tumor suppressor gene, with most mutations occurring in the exons." (PMID 33004005, 2020). "However, our findings are only the first step towards understanding what drives quiescent HBs into growth and may offer novel ways to both detect and prevent growth in VHL-associated hemangioblastomas." (PMID 27748427, 2016). "In this study, formalin-fixed, paraffin-embedded (FFPE) samples obtained from both VHL-related and sporadic hemangioblastoma patients were utilized for immunohistochemical characterization of FGFR1–4." (PMID 40393028, 2025). "Patients 22 and 23 were positive for VHL:c.345C>A and VHL:c.532C>G, respectively, each presenting with one component tumor: a hemangioblastoma and a paraganglioma." (PMID 40647474, 2025). "Although primary hemangioblastoma cultures were successfully established from 9 out of 12 tumor samples obtained from patients diagnosed with VHL, a low-prevalence disease, the overall sample size remains limited." (PMID 40427061, 2025). "Once VHL was confirmed, craniotomy with excision of the cerebellar lesion was performed and the diagnosis of hemangioblastoma was confirmed by pathology." (PMID 40918781, 2025). "ZHX2 was ubiquitinated in Scl+hemangioblastoma-like cells after the transfer of the VHL expression vector into these cells." (PMID 39850947, 2024). "Our previous research showed the expression of Brachyury and TAL1 in 10 of 10 VHL-related hemangioblastomas." (PMID 37174017, 2023). "Based on our data, the clinical Danish criteria specificity is not comparable to genetic testing and is inferior to the International criteria that are based on unique clinical manifestations of VHL (mainly multiple hemangioblastomas)." (PMID 36980542, 2023). "Careful family history and screening for other VHL-related tumors, in all patients who undergo hemangioblastoma genetic testing for VHL disease, is recommended." (PMID 36358771, 2022). "We compared the median onset age between both groups, which suggested that there was a significant difference between sporadic (median age: 42.50 years) and VHL-related hemangioblastoma (median age 33.00 years) (p = 0.010)." (PMID 36760665, 2022). "Despite few studies having reported the efficacy of RT for supratentorial hemangioblastoma, studies on CNS hemangioblastoma have shown that the 5-year OS of the VHL subgroup was better than that of the non-VHL when patients were stratified by VHL status." (PMID 36760665, 2022). "VHL- and RCC-related deaths have decreased over time, with hemangioblastoma representing the first cause of death in this population." (PMID 36358771, 2022). "A comparison of tumor volumes between sporadic and VHL-related supratentorial hemangioblastomas revealed that the volume in the former was significantly larger than that of the latter (p < 0.0001)." (PMID 36760665, 2022).
hemangioblastoma (continued). "This intriguing finding provided a mechanistic rationale for the clinical testing of dovitinib, a multi-kinase inhibitor targeting FGFR, VEGFR, and PDGFR, in patients with genetically-confirmed VHL and at least one measurable hemangioblastoma." (PMID 36358730, 2022). "VHL type 2, which is predominantly associated with VHL missense mutations, is defined by the occurrence of PPGL, either alone (type 2C) or with hemangioblastomas (type 2A) or with hemangioblastomas and renal cell carcinomas (type 2B)." (PMID 36733351, 2022). "We collected a cohort of 13 supratentorial hemangioblastoma patients diagnosed at the Xiangya Hospital, Central South University, between the years 2010 and 2021, with the breakup being four VHL-related and nine sporadic supratentorial hemangioblastomas." (PMID 36760665, 2022). "For instance, we cannot differentiate between sporadic hemangioblastomas and VHL-related hemangioblastomas within the SEER database, which would have been important in the survival analysis." (PMID 33014882, 2020). "In VHL-related hemangioblastomas, bi-allelic inactivation of the VHL gene can induce HIF stabilization." (PMID 30971719, 2019). "Recently a high-resolution genome-wide view of chromosomal changes in sporadic hemangioblastoma identified 23 candidate genes beyond VHL for hemangioblastoma pathogenesis." (PMID 31087189, 2019). "In this work, we demonstrate the therapeutical properties of ICI-118,551 in VHL-derived CNS-Hemangioblastoma primary cultures, becoming a promising drug for VHL disease and other HIF-related diseases." (PMID 31296894, 2019). "Angiogenesis is dependent on the activation of HIF program, constitutively active in VHL hemangioblastomas." (PMID 31296894, 2019). "Recent studies have suggested that the inactivation of VHL plays a dominant role not only in the pathogenesis of familial hemangioblastomas but also in the sporadic form." (PMID 30971719, 2019). "The clinical diagnosis of VHL disease can be made if a single VHL associated tumor (hemangioblastoma, PHEO or RCC) occurs in a patient with a family history of VHL." (PMID 28388566, 2017). "Inactivation of the VHL tumour suppressor gene is a highly frequent genetic event in the carcinogenesis of central nervous system-(CNS) hemangioblastomas (HBs)." (PMID 28710479, 2017). "For example, previous results were obtained from VHL-related hemangioblastomas using techniques that identify deletions that are larger than 2 Mb." (PMID 26768750, 2016). "Most interestingly, sporadic hemangioblastomas overexpress CXCR4 compared to VHL-related hemangioblastoma." (PMID 26920352, 2016). "This reiterates the need for elucidating other genetic alterations specific for hemangioblastoma beside the hits of VHL gene." (PMID 26768750, 2016). "We also determined the genetic background of hemangioblastomas of both VHL-related and sporadic cases." (PMID 26920352, 2016). "In sporadic hemangioblastomas the mean percentage of CXCR4 positive hemangioblastoma cells was 16 %, SD 8.4, in VHL-related hemangioblastomas 8 %, SD 4.4 (P = 0.002)." (PMID 26920352, 2016). "Hemangioblastomas are sometimes referred to as vascular tumors; however, biallelic inactivation of VHL was detected in the stromal compartment of the vascular tumors, which also have a clear cell appearance." (PMID 27733136, 2016). "To analyze the possible reason for the observed difference we determined the genetic background of hemangioblastomas of both VHL-related and sporadic cases." (PMID 26920352, 2016). "In two out of 27 hemangioblastomas specimens the VHL promoter was hypermethylated, both were sporadic hemangioblastoma cases." (PMID 26920352, 2016). "VEGFA was expressed higher than normal in sporadic and VHL-related hemangioblastomas, and present in stromal hemangioblastoma cells and vascular endothelial cells." (PMID 26920352, 2016).